FOSB (FosB proto-oncogene, AP-1 transcription factor subunit)
Diseases named in the same sentence as FOSB in open-access papers (continued):
Sharing a sentence is not in itself a finding about the gene and the disease.
epilepsy (7 papers, 2015 to 2025). A brain disorder characterized by episodes of abnormally increased neuronal discharge resulting in transient episodes of sensory or motor neurological dysfunction, or psychic dysfunction. "Additionally, FosB/ΔFosB isoforms were directly involved in epileptogenesis since their deletion was associated with adult-onset spontaneous epilepsy." (PMID 28018175, 2016). "In particular, we evaluated the expression of FosB/ΔFosB antigens, which are known to be markedly induced either in seizure models, or in models of epilepsy." (PMID 28018175, 2016). "In addition, to map neuronal activation, we used an antibody against FosB/ΔFosB-related antigens, which were previously characterized as reliable markers in different models of epilepsy." (PMID 26555229, 2015). "rs148726219 is located within intron 2 of the FOSB gene (ENST00000353609.8), a member of the AP-1 complex which has an exceptionally stable splice isoform (ΔFOSB, ENST00000615753.4, ENST00000592436.5) that has been previously implicated in addiction, epilepsy, and cognition." (PMID 37751459, 2023). "We further assessed changes in the expression of FosB and GFAP during the chronic phase of epilepsy through immunofluorescence staining and Western blotting." (PMID 40170730, 2025). "Immunofluorescence staining and Western blotting data on FosB and GFAP expression confirmed the increased excitability of medial parabrachial nucleus neurons and enhanced astrocyte reactivity during the chronic epilepsy phase." (PMID 40170730, 2025).
epithelioid hemangioma (7 papers, 2017 to 2024). A hemangioma characterized by the presence of epithelioid endothelial cells. "The FOSB fusions described in atypical epithelioid hemangioma and pseudomyogenic hemangioendothelioma occur at the N-terminal part of the protein and are most likely induced by promoter swap events, causing upregulation of FOSB." (PMID 31768625, 2020). "Chromosome translocations involving the FOS gene have been identified as a genetic hallmark of epithelioid hemangioma, whilst rearrangements involving FOSB have been detected in pseudomyogenic hemangioendothelioma and in a subset of epithelioid hemangioma, defined as cellular/atypical variant." (PMID 33114111, 2020). "Cases of epithelioid hemangioma and pseudomyogenic hemangioendothelioma have shown WWTR1::FOSB gene fusions." (PMID 40491864, 2024). "An interesting note is that in benign human epithelioid hemangiomas, ZPF36 and FOSB form a fusion product." (PMID 29073243, 2017).
pancreatic cancer (7 papers, 2017 to 2025). "For example, in patients with pancreatic cancer with lymph node metastasis, the RGS16 and FosB expression is markedly reduced in pancreatic cancer andis closely associated with a decreased survival rate of patients." (PMID 36120550, 2022). "Meanwhile, previous studies have found that the expression levels of RGS16 and FosB were significantly reduced in pancreatic cancer with lymph node metastasis." (PMID 32319728, 2020). "We also observed the differential methylation of four pancreatic cancer marker genes, i.e., FOSB, KLF6, ATP4A, GSG1, related to survival of patients." (PMID 28423671, 2017). "The published article titled “miR-144-3p targets FosB proto-oncogene, AP-1 transcription factor subunit (FOSB) to suppress proliferation, migration, and invasion of PANC-1 pancreatic cancer cells” has been retracted from Oncology Research, Vol." (PMID 40109868, 2025). "We observed differential methylation of FOSB, KLF6, ATP4A, and GSG1 genes that are previously reported as markers for pancreatic cancer survival." (PMID 28423671, 2017). "miR-144-3p was significantly downregulated in hepatocellular carcinoma, glioblastoma, multiple myeloma and pancreatic cancer and inhibited proliferation, migration and tumour metastasis by targeting SGK3, FZD7, c-Met and FOSB." (PMID 31552107, 2019).
papillary thyroid cancer (7 papers, 2012 to 2025). "We investigated whether coding single-nucleotide polymorphisms (cSNPs) and promoter SNPs of FOSB contribute to the development of papillary thyroid cancer (PTC)." (PMID 23181129, 2012). "For example, in papillary thyroid cancer, FOSB was validated to play an oncogenic role with promoting modulation of cell growth, migration and invasiveness." (PMID 41272900, 2025). "Many previous studies have reported the regulatory role of FOSB in the growth and metastasis of papillary thyroid cancer,35breast cancer,36nonsmall cell lung cancer,37prostate cancer,38and other tumors." (PMID 37501756, 2023). "Moreover, it has been reported that KAT5 recruited by FosB contributes to metastasis and growth of papillary thyroid cancer." (PMID 34406978, 2021). "FosB recruits KAT5 to potentiate proliferation and metastasis of papillary thyroid cancer cells via modulating DPP4 function." (PMID 35392432, 2022). "As far as the papillary thyroid carcinomas are concerned, FOS, FOSB and EGR1 genes were down-regulated, like CBX7, while SPP1, SPINK1 and STEAP1 were up-regulated." (PMID 24865347, 2014).
periodontitis (7 papers, 2015 to 2026). An acute or chronic inflammatory process that affects the tissues that surround and support the teeth. "Additional genes encoding FOS and JUN family members (JUNB, FOSB, FOSL1) were significantly downregulated in periodontitis." (PMID 41124422, 2025). "Using the same transcriptomic database (GESE16134), FOSB was identified as an upregulated DEG with potential participation in periodontitis." (PMID 38241313, 2024). "In conclusion, this study identified several genes (CTSS, PLEK, IRF-8, PTGS2 and FOSB) that involved in the development and progression of periodontitis." (PMID 26334995, 2015). "This study identified genes (CTSS, PLEK, IRF-8, PTGS2, and FOSB) that may be involved in the development and progression of periodontitis." (PMID 26334995, 2015). "Thus, we suggested that PTGS2 might play a critical role in periodontitis progression involving in TCR signaling pathway via interacting with FOSB." (PMID 26334995, 2015). "A total of 13 crosstalk genes were differentially coexpressed with four neuropeptides, whereby FOSB was highly expressed in MDD and periodontitis." (PMID 34721734, 2021). "The neuropeptide genes ADM, IGF2, PDYN, and RETN were intersected between periodontitis and MDD, and FOSB was a crosstalk gene related to these neuropeptides on the transcriptomic level." (PMID 34721734, 2021).
atherosclerosis (6 papers, 2023 to 2025). A disease characterized by the build-up of fatty material and calcium deposition in the arterial wall resulting in partial or complete occlusion of the arterial lumen. "ST analysis showed that IGF-1 suppressed FOS/FOSB factors and gene expression of MMP9 and CXCL14 in plaque macrophages, suggesting possible involvement of these molecules in IGF-1’s effect on atherosclerosis." (PMID 36602878, 2023). "FOSB was upregulated in plaque only, similarly to CD4+ C3, and JUNB expression was increased in PSA compared to atherosclerosis." (PMID 38665903, 2023). "ST analysis revealed that IGF‐1 inhibited gene expression of FOS/FOSB factors, as well as MMP9 and CXCL14 in plaque macrophages, these molecules may be involved in the IGF‐1 effect on atherosclerosis." (PMID 40156163, 2025).
COVID-19 (6 papers, 2022 to 2025). A disease caused by infection with severe acute respiratory syndrome coronavirus 2. "We also found lower expression of FOSB in severe COVID-19 and septic shock patients." (PMID 38892107, 2024). "The gene FOSB was found to be expressed in higher amounts in the mild forms of sepsis and COVID-19." (PMID 38892107, 2024). "In our investigation, we have identified significant transcriptomic alterations, particularly in the genes CD3, CD14, CD16, FOSB, S100A12, and TCRɣδ, that differentiate sepsis, mild COVID-19, septic shock, and severe COVID-19." (PMID 38892107, 2024). "Patients with COVID-19 showed downregulation of genes involved in the AP-1 transcription factor pathway (including JUN, JUNB, JUND, and FOSB) as well as HLA genes (including HLA-E, HLA-DRB1, HLA-DRA, and HLA-DPB1)." (PMID 36992700, 2023). "FOSB inactivation in mast cells has been shown to increase the inflammatory response, and it has contradictorily also been reported to be upregulated in single cell analysis of CD4+ T-cells of severe COVID-19 patients." (PMID 35438176, 2022).
glioblastoma (6 papers, 2019 to 2023). The most malignant astrocytic tumor (WHO grade IV). "FBJ murine osteosarcoma viral oncogene homolog B (FOSB) also mediated the SCD-dependent acquire-resistance in glioblastoma cell lines." (PMID 35646898, 2022). "The Transwell assay demonstrated that the glioblastoma cell lines had lower migration ability after the knockdown of FOSB." (PMID 36311014, 2022). "In this study, we aimed to explore the expression of FOSB in glioma and its biological role in glioblastoma multiforme (GBM)." (PMID 36311014, 2022).
melanoma (6 papers, 2009 to 2025). A malignant, usually aggressive tumor composed of atypical, neoplastic melanocytes. "We observed that while the levels of cFOS remained stable, FOSB levels increased significantly in AqR GBM and melanoma cells." (PMID 33568479, 2021). "Moreover, we demonstrate that tumor-relevant genes, such as FosB, WEE1, PVR, MAP1LC3B, and LGALS3, are deregulated in melanoma by direct regulation via c-Jun5." (PMID 31378787, 2019). "Depletion studies using the DepMap database revealed that silencing FRA1, but not other FOS family members (FOS, FOSB, FRA2), significantly reduces cell viability in melanoma and across multiple cancer types." (PMID 41286309, 2025).
triple-negative breast carcinoma (6 papers, 2016 to 2025). An invasive breast carcinoma which is negative for expression of estrogen receptor (ER), progesterone receptor (PR), and human epidermal growth factor receptor 2 (HER2). "In triple-negative breast cancer, a significant reduction in FOSB promotes cell proliferation and tumor growth." (PMID 40361912, 2025). "The authors reported that tilapia piscidin 4 (TP4), derived from Oreochromis niloticus, induces an activator protein-1 (AP-1) protein named FosB through disrupting calcium homeostasis in triple-negative breast cancer (TNBC) cells." (PMID 35280755, 2022). "In a previous study on triple-negative breast cancer cells, TP4 was shown to induce FOSB activation via elevation of intracellular calcium." (PMID 33562681, 2021).
viral infection (6 papers, 2017 to 2024). "FOSB is 70% homology with Fos, which together with the Jun family members form the group of AP-1 proteins which modulated the gene expression in response to cytokines, growth factors, bacterial and viral infections." (PMID 35941292, 2022). "Based on interaction analysis, miR-324-3p mainly regulated FOSB, MX1, and IFIH1, which can inhibit transcription and replication in the early stages of viral infection, and stimulate to produce the innate immune response." (PMID 38178220, 2024). "The CD8+ T cell-specific clonotype, however, was only expressed in T cells that had little expression of CD69, FOS and FOSB, suggesting that this was not an active viral infection." (PMID 38665903, 2023). "Compared to mRNA purified from WT controls, mRNA from floxed FosB mice showed a nearly complete absence of FosB gene expression, indicating that our purified mRNA comes from vHPC neurons projecting to NAc, as retrograde viral infection in NAc is the only source of Cre in these animals." (PMID 32901027, 2020). "Since FOS, FOSB and NR4A1 gene expression was consistently lacking in epithelial transcriptional responses to SARS‐CoV‐2, we next investigated their contribution to viral infection by modulation of their activity, or modulation of related signalling pathways, using small molecules." (PMID 38623540, 2024).
bone tumors (5 papers, 2018 to 2026). "The aim of this study was to evaluate whether the recently found FOS and FOSB rearrangements can be used as an auxiliary diagnostic tool in routine bone tumor diagnosis." (PMID 31768625, 2020). "Overall, our findings reveal a human bone tumour defined by mutations of FOS and FOSB." (PMID 29858576, 2018).
glioma (5 papers, 2022 to 2024). A benign or malignant brain and spinal cord tumor that arises from glial cells (astrocytes, oligodendrocytes, ependymal cells). "FOSB has been reported to be highly expressed in glioma tissue compared to normal brain and is associated with glioma cell proliferation, migration, and invasion." (PMID 36937401, 2023). "On the other hand, C5 FOSB+ Glioma cells were enriched in responses to protein misfolding, temperature changes, and topologically incorrect proteins." (PMID 39403379, 2024). "In conclusion, we found that FOSB was overexpressed in human glioma tissues and GBM cell lines compared with normal human brain tissues and astrocyte lines, respectively." (PMID 36311014, 2022). "FOSB expression in U87 and U251 cell lines was higher than in other glioma cell lines, and thus U87 and U251 cell lines were selected for lentiviral transfection." (PMID 36311014, 2022). "Western blot results showed that FOSB expression in U251, U87, T98G, and A172 glioma cell lines was higher than in HA, especially in U251 and U87." (PMID 36311014, 2022). "Immunohistochemistry and immunofluorescence were used to detect the expression of FOSB in glioma tissues." (PMID 36311014, 2022). "The viability of glioma cells decreased, and the ability of glioma cells to proliferate and migrate was reduced when FOSB was downregulated." (PMID 36311014, 2022). "Quantitative reverse transcriptase polymerase chain reaction (RT-qPCR) results showed that the expression of FOSB in each of the five glioma cell lines was higher than that in the human astrocyte cell line at the mRNA level." (PMID 36311014, 2022). "FOSB knockdown significantly inhibited the invasion of glioma cells compared with the control group." (PMID 36311014, 2022). "Compared with normal brain tissues, we found that FOSB was highly expressed in glioma tissues both at the protein and mRNA levels." (PMID 36311014, 2022). "We classified the 40,650 astrocytomas obtained by Seurat and named the seven subclusters according to the marker genes as C0 IGFBP7+ Glioma cells, C1 OLIG2+ Glioma cells, C2 LINC02283+ Glioma cells, C3 LINC00632+ Glioma cells, C4 MX1+ Glioma cells, C5 FOSB+ Glioma cells, and C6 DLL3+ Glioma cells." (PMID 39403379, 2024). "The present study determined the expression of FOSB in glioma tissues and cell lines." (PMID 36311014, 2022). "FOSB expression in glioma was higher than that in normal brain tissue." (PMID 36311014, 2022). "Interestingly, FOSB expression in U118 glioma cells was lower than that in normal HA, but FOSB mRNA expression was significantly higher in U118 than in HA." (PMID 36311014, 2022). "FOSB expression was higher in glioma compared with normal brain tissue." (PMID 36311014, 2022). "Finally, subcutaneous tumorigenesis in nude mice was used to observe the tumorigenesis of glioma cell lines after the knockdown of the FOSB gene." (PMID 36311014, 2022). "In addition, the expression of FOSB in high-grade glioma was much higher than that in low-grade glioma." (PMID 36311014, 2022). "Compared with the control, knockdown of FOSB could significantly inhibit the proliferation of glioma cell lines." (PMID 36311014, 2022). "In addition, the CCK-8 experiment also confirmed that the proliferation of glioma cell lines decreased after the knockdown of FOSB." (PMID 36311014, 2022). "However, the expression and role of FOSB in glioma remain obscure." (PMID 36311014, 2022). "The down-regulation of FOSB could affect the growth of glioma cells transplanted to nude mice." (PMID 36311014, 2022). "Interestingly, after the knockdown of FOSB, the proliferation of gliomas was further inhibited." (PMID 36311014, 2022). "Hence, we attempted to detect whether FOSB had any effects on the proliferation and invasion of glioma cells and whether the resistance of glioma cell lines to TMZ was affected by FOSB knockdown." (PMID 36311014, 2022). "However, the biological function of FOSB in glioma remains unclear." (PMID 36311014, 2022).
glioma (continued). "Hence, FOSB may promote the development and migration of gliomas." (PMID 36311014, 2022). "Moreover, downregulating FOSB could significantly reduce the proliferation, migration, and TMZ resistance of glioma." (PMID 36311014, 2022). "However, there are no studies on the expression and mechanisms of FOSB in glioma." (PMID 36311014, 2022).
Parkinson disease (5 papers, 2014 to 2025). A progressive degenerative disorder of the central nervous system characterized by loss of dopamine producing neurons in the substantia nigra and the presence of Lewy bodies in the substantia nigra and locus coeruleus. "Similarly, p-ERK1/2 and FosB/ΔFosB were also upregulated in a model of Parkinson’s disease." (PMID 28018175, 2016).
thyroid cancer (5 papers, 2014 to 2024). "It has been recently reported that the KAT5 served as a transcriptional partner of FOSB to potentiate thyroid cancer growth and metastasis by enhancing FOSB-mediated transcriptional activation of DPP4." (PMID 39164746, 2024). "Zhang and his colleagues showed that HSF2 regulates FosB in thyroid carcinoma development." (PMID 36430241, 2022). "Bioinformatics analysis of RNA-sequencing data suggested that HSF2 may be associated with the development of thyroid carcinoma by regulating SERPINA1 and FOSB expression." (PMID 34917120, 2021). "Through this analysis, they thought that HSF2 is involved in thyroid carcinoma development by regulating SERPINA1 and FosB genes." (PMID 36430241, 2022). "Bioinformatics analysis has demonstrated that HSF2 may be involved in the oncogenesis of thyroid carcinoma by mediating the expression of SERPINA1 and FOSB." (PMID 35087869, 2021).
cocaine addiction (4 papers, 2016 to 2022). "Herein, we provide evidence that miR-1 targets the mRNA encoding the transcription factor FosB, the spliced version of which, ∆FosB, persistently accumulates in D1-SPN of the NAc after chronic psychostimulant exposure, and plays a key role in cocaine addiction." (PMID 34785784, 2022). "Moreover, ATF2, CREB1, CREB5, and FOSB in all three substance diseases (alcoholism, amphetamine, and cocaine addiction pathways)." (PMID 30899073, 2019). "Our recent work demonstrates that HPC ΔFosB plays a critical role in learning, and thus the decrease in HPC FosB gene expression in cocaine addicts shown here may represent a mechanism for cognitive decline in psychostimulant addiction." (PMID 27494187, 2016). "Among up- and downregulated genes from the pathway hsa05030:cocaine addiction are genes JUN, GNAS, BDFN, and CDK5R1 (upregulated), and FOSB, NFKB1, CREB1 and PPP1R1B (downregulated)." (PMID 34947877, 2021). "(Alcoholism, amphetamine addiction, cocaine addiction) ATF2, CREB1, CREB5, and FOSB in all three substance disease KEGG pathways are suspected be related with CREB and FOS family, and JUN." (PMID 30899073, 2019).